CLDN34 (claudin 34)
Description:
Plays a major role in tight junction-specific obliteration of the intercellular space, through calcium-independent cell-adhesion activity.
Tractability: Antibody: UniProt places it where antibodies can reach, with medium confidence; UniProt predicts a signal peptide or a membrane-spanning region; its Gene Ontology location is reachable by antibodies, with medium confidence.
Gene: Protein-coding gene on chromosome X (9,961,424 to 9,968,352, forward strand). Ensembl gene ENSG00000234469.
Subcellular location: Cell junction, tight junction; Cell membrane
Gene Ontology:
Molecular function: structural molecule activity
Cellular component: bicellular tight junction; plasma membrane
Homologues: Orthologues: chimpanzee CLDN34 (98% identical), rat Cldn34a (43% identical), rat Cldn34e (41% identical), mouse Cldn34a (40% identical), mouse Cldn34c4 (38% identical), rat Cldn34b4 (38% identical), rat Cldn34c4 (37% identical), rat Cldn34b3 (37% identical), rat Cldn34d (37% identical), mouse Cldn34b4 (36% identical), rat Cldn34b (36% identical), mouse Cldn34b3 (36% identical), and 9 more. Paralogues in human: CLDN24 (21% identical), CLDN22 (20% identical), CLDN6 (20% identical), CLDN19 (20% identical), CLDN1 (19% identical), CLDN18 (18% identical), CLDN2 (18% identical), CLDN3 (18% identical), CLDN14 (18% identical), CLDN17 (18% identical), CLDN4 (18% identical), CLDN25 (17% identical), and 10 more.
Diseases named in the same sentence as CLDN34 in open-access papers:
CLDN34 is named in the same sentence as 2 diseases in open-access papers, as found by Europe PMC text mining. Sharing a sentence is not in itself a finding about the gene and the disease.
CLDN34 shares sentences with these, for which no sentence is quoted: allergies (1 paper); celiac disease (1).